LOX (lysyl oxidase)
Diseases named in the same sentence as LOX in open-access papers (continued):
Sharing a sentence is not in itself a finding about the gene and the disease.
pulmonary fibrosis (continued). "The deficiency of Lysyl oxidase (LOX) or Lysyl Oxidase-like Proteins (LOX/Ls) significantly reduced collagen accumulation in lungs of murine model of pulmonary fibrosis, since processed collagen (cross-linked collagen) could not be efficiently degraded by collagen degrading enzymes." (PMID 35370755, 2022). "LOX can also modulate TGF-β via a feedback loop which is active in skeletal muscle development and idiopathic pulmonary fibrosis." (PMID 32708046, 2020). "In order to further validate our findings from the in vitro expression experiments, we next analyzed LOX/L RNA and protein expression in the Bleomycin (BLM) induced lung fibrosis model." (PMID 28273952, 2017). "Here, we systematically investigated LOX/L expression in primary fibroblasts and epithelial cells under fibrotic conditions, Bleomycin (BLM) induced lung fibrosis and in human IPF tissue." (PMID 28273952, 2017). "YAP regulates the expression and secretion of the ECM modifying enzyme lysyl oxidase (LOX) in fibrotic alveolar cells, which represents a previously unknown mechanism for AT2 cells to contribute to pulmonary fibrosis." (PMID 40753090, 2025). "YAP regulates the expression and secretion of the ECM modifying enzyme lysyl oxidase (LOX) in fibrotic AT2 cells, which represents a previously unknown mechanism for AT2 cells to contribute to pulmonary fibrosis." (PMID 40753090, 2025). "In addition to primary lung cells, we further analyzed protein expression and cellular distribution of LOX/L family members by immunohistochemistry in lung tissue samples derived from both, BLM-induced lung fibrosis in mice and 14 human IPF patients." (PMID 28273952, 2017). "In addition, the development and progression of pulmonary fibrosis is influenced by LOXL2, and LOX may be connected to the TGF-β signaling pathway." (PMID 37275755, 2023). "As our studies do not unequivocally exclude a potential role for other LOX/LOXL family members in human lung fibrosis an area of future study could be the systematic silencing of each LOX/LOXL family member using CRISPR gene editing." (PMID 35188460, 2022). "Increased levels of lysyl oxidase (LOX), an amine oxidase critical for the initiation of collagen and elastin cross-linking, increased mRNA levels of collagen type I (Col1a2), collagen type III (Col3a1) and matrix metalloproteinase (Mmp2) have been reported in murine models of lung fibrosis." (PMID 24204629, 2013).
breast tumor (34 papers, 2011 to 2025). "Increased LOX activity and expression, fibrillary collagen cross-linking, and focal adhesion signaling observed after breast tumor resection contribute to increasing the risk of lung metastases." (PMID 33669630, 2021). "Breast tumour-associated fibroblasts over-express lysyl oxidase, stiffening the matrix and leading to increased tumour cell invasion." (PMID 30348208, 2018). "We and others have further shown that LOX expression is associated with the ER status in breast tumours." (PMID 25141126, 2014). "In one of their other studies, it was revealed that LOX, secreted by hypoxic breast tumor cells, accumulates at pre - metastatic sites." (PMID 40661776, 2025). "The use of LOX inhibitors, such as Pdcd4 and β-aminopropionitrile, decreases the invasive capacity of the breast tumor cell lines T47D and MCF7 and reverses LOX-induced EMT, invasion and metastasis in cervical cancer." (PMID 36497411, 2022). "Blocking LOX-like 2, a member of the LOX enzyme family, alters collagen fibril thickness and organization, in turn disrupting human breast tumor cell motility, adhesion, and invasion." (PMID 35205605, 2022). "The HMGA2/miR-200b/LOX axis plays an important role in the initial stages of breast tumor cell invasion and metastasis." (PMID 33668453, 2021). "The AMT inhibitors are selective for LOX/LOXL2 and led to a significant reduction in tumor growth and metastases in an in vivo model of transgenic LOX-dependent breast tumor mice." (PMID 33669630, 2021). "For example, hypoxic primary breast tumor environments release lysyl oxidase (LOX), triggering NFACTc1-driven osteoclastogenesis, which increases bone resorption and thereby creates a metastatic niche for circulating tumor cells." (PMID 33968034, 2021). "Both decreased and increased expression of LOX enzymes were shown in breast tumor tissue compared to healthy breast tissues." (PMID 34838055, 2021). "Expression of lysyl oxidase is often upregulated in hypoxic breast tumors and indeed appears to be required for tumor growth and metastasis." (PMID 28750038, 2017). "HMGA2 has been suggested to mediate breast tumor metastasis by promoting the expression of LOX and syndecan-2." (PMID 25868853, 2015). "LOX expression is induced by hypoxia-inducible factor (HIF) through a hypoxia-responsive element in the LOX promotor, and is associated with hypoxia in breast tumours." (PMID 25141126, 2014). "Bisphosphonate treatment inhibits bone osteoclasts, which could be a potential combination therapeutic for patients with high-LOX primary breast tumors." (PMID 33968034, 2021). "EDIL-3 could activate EGF receptor (EGFR) signaling to promote bladder cell migration, and lysyl oxidase secreted by hypoxic breast tumor cells was considered to be a crucial mediator of pre-metastatic niche formation." (PMID 28706483, 2017). "TGF-β has been shown by others to upregulate LOX in prostate and breast tumor cells and aggressive prostate cancer cells expresses more TGF-β than indolent tumors and high TGF-β expression in tumor epithelial cells is associated with a poor outcome in our cohort of prostate cancer patients." (PMID 26501565, 2015). "LOX expression can be induced by hypoxia via HIF1, and a hypoxia response signature identified by expression profiling is also associated with ER status in breast tumours." (PMID 25141126, 2014). "Accordingly, LOX (lipooxygenase) may be secreted by primary breast tumours." (PMID 37375846, 2023). "MiR-200 directly inhibits Lysyl oxidase (LOX) expression, leading to inhibition of breast tumor invasion." (PMID 33668453, 2021). "We observed a significant increase in LOX and CCL2 expression in the lungs of mice bearing triple-negative SUM159 breast tumors relative to lungs from mice bearing luminal A MCF7 tumors or tumor-naïve mice." (PMID 31936750, 2020).
breast tumor (continued). "Lysyl oxidase (LOX), an enzyme, important in collagen turnover and secreted by hypoxic breast tumor cells, was shown to accumulate at pre-metastatic sites where it caused crosslinking of collagen IV in the basement membrane." (PMID 28494752, 2017). "Lysyl oxidase, LOXL2, or LOXL4 expression in the primary breast tumor leads to pre-metastatic deposition of collagen I in the lungs of mice, favoring the formation of metastases in the lungs." (PMID 26539408, 2015). "Both HIF-1 and XBP1s are reported to upregulate lysyl oxidase (LOX) in the estrogen receptor-negative breast tumors and thus promote a pre-metastatic niche formation." (PMID 36230792, 2022). "Additionally, Pn is known to promote myeloid-derived suppressor cells (MDSC)-mediated pulmonary premetastatic niche formation during breast tumor metastasis through S100A8/9 and LOX." (PMID 34680221, 2021). "In the context of bone metastases, lysyl oxidase (LOX) is secreted by estrogen receptor–negative (ER−) breast tumors and mediates PMN formation in the bone." (PMID 32850317, 2020). "LOX was shown to be co-localised with fibronectin in sites of future metastasis, where it facilitated matrix remodelling, enhanced CD11b+ BMDC recruitment, and increased metastasis after being secreted from the hypoxic tumour environment of primary breast tumours." (PMID 37375846, 2023). "NAC treatment was therefore able to prevent the stabilization of Hif-1α and reduce VEGF secretion in response to hypoxia in both PyMT and EO771 breast tumor cells in vitro, but not alter the hypoxia-induced gene expression of VEGF and LOX." (PMID 23840457, 2013).
prostate carcinoma (34 papers, 2013 to 2025). A carcinoma that arises from epithelial cells of the prostate gland. "However, another study suggested that low LOX expression in tumors detected by immunohistochemistry was associated with a poor prognosis in patients with prostate cancer." (PMID 38255186, 2023). "LOX encodes a member of the lysyl oxidase family proteins, which has previously been proposed to promote epithelial to mesenchymal transition in prostate cancer, and its propeptide domain may display tumor suppressor activities." (PMID 32849815, 2020). "Furthermore, a high TINT epithelial LOX score was associated with an increased relative risk for prostate cancer specific death in a univariate Cox regression analysis." (PMID 26501565, 2015). "High LOX expression has been associated with increased metastasis and poor prognosis in a number of different tumour types such as breast, colorectal, head and neck, and prostate cancer." (PMID 25141126, 2014). "The selective cytotoxicity of flavone glycoside-enriched fractions and the LOX-inhibitory activity of phenylethanoid-enriched fractions underscore possible applications in prostate cancer and inflammation-related conditions." (PMID 41225814, 2025). "By contrast, the propeptide domain of LOX (LOX-PP) derived from the pro-LOX has been shown to inhibit breast, pancreatic, lung, and prostate cancers." (PMID 37298359, 2023). "uPARAP/Endo180 expressed by stromal cells associated with the cross-linking of collagen fibers by stromal-derived lysyl oxidase (LOX) regulates the migration of metastatic prostate cancer cells." (PMID 35460056, 2022). "We showed that LOX expression decreased in the more advanced and aggressive castration-resistant prostate cancer (CRPC), compared to castration-sensitive prostate cancer (CSPC)." (PMID 35003355, 2021). "Studies have shown that LOX mRNA level was increased in various cancer types, including head and neck squamous cell carcinoma, and breast and prostate cancers." (PMID 32849853, 2020). "Results presented here warrant further research in larger samples in order to evaluate the predictive and prognostic value of KDR and LOX SNPs in prostate carcinoma." (PMID 28143503, 2017). "Infact decreased LOX activity has been reported in the prostate cancer, high-grade prostatic intraepithelial neoplasia and human colon cancer and therefore represent a research question which needs to be addressed to its full." (PMID 27473871, 2016). "Our results suggest that the enzymatic function of LOX is highly context-dependent and that it can have both tumour-suppressing and tumour-promoting properties in prostate cancer." (PMID 26804196, 2016). "In this paper we explored the role of two emerging anti-metastatic targets involved in collagen matrix homeostasis, Endo180 and LOX, in directing the plasticity of metastatic prostate cancer cells on human ECM surfaces." (PMID 26567111, 2016). "The concomitant decrease in PC3 cell migration and increase in Endo180 expression induced by stromal LOX inhibition indicates that the Endo180-dependent rounded mode of prostate cancer cell migration requires ECM crosslinking." (PMID 26567111, 2016). "Overexpression of LOX has also been reported in variety of tumors including breast, colorectal and prostate cancer." (PMID 27473871, 2016). "In summary we find that LOX staining score in prostate TINT epithelium predicted prostate cancer specific survival and gave additive prognostic information to GS." (PMID 26501565, 2015). "Previous studies in a rat model suggested that the presence of a prostate cancer increased LOX expression not only in the tumor but also in the rest of the tumor bearing prostate lobe." (PMID 26501565, 2015). "LOX levels both in tumors and in the surrounding tumor-bearing organ are apparently related to prostate cancer aggressiveness." (PMID 26501565, 2015).
prostate carcinoma (continued). "We found thatbaicalein inhibition of 12/15-LOX contributes to its induction of neuronal VEGF,which coincides with previous studies showing that LOX activity inhibits VEGFgene expression in skeletal muscles and prostate cancer cells." (PMID 23904909, 2013). "The role of LOX in prostate cancer is controversial since some studies suggest that downregulation of LOX promotes the progression of prostate cancer, while other studies have shown that inhibition of LOX enzymes initiated before implantation of AT-1 cells reduces prostate tumor growth." (PMID 38255186, 2023). "Studies have shown that LOX may inhibit the progression of prostate cancer (PCa), whereas other studies demonstrate that LOX may act as a tumor activator in PCa." (PMID 35003355, 2021). "The role of lysyl oxidase (LOX) in prostate cancer remains controversial." (PMID 35003355, 2021). "Moreover, the depletion of RB1 from RB1-proficient prostate cancer cells promoted gain of stem cell-like properties through increased expression of interleukin-6 (IL-6) and lysyl oxidase (LOX)." (PMID 34359636, 2021). "Multiple studies agree that the LOX propeptide may suppress tumor growth, but the role of LOX in prostate cancer remains controversial." (PMID 29732010, 2018). "In this study we observed that the inherited genetic variants in LOX and KDR seem to modulate the expression of LOX and VEGFR2 in carcinoma cells, supporting a gene-tumor microenvironment interaction in the activation of hypoxia-driven pathways in prostate carcinoma." (PMID 28143503, 2017). "Two genetic polymorphisms (LOX +473 G > A and KDR−604 T > C) were correlated with protein level, accounting for a potential gene-environment effect in the activation of hypoxia-driven pathways in prostate carcinoma." (PMID 28143503, 2017). "Interestingly, previous reports showed significantly increased expression of LOX mRNA in prostate carcinomas compared to nodular prostate hyperplasia, whereas stronger LOX expression was also observed in other solid malignancies." (PMID 28143503, 2017). "In summary, we show that high LOX expression in the tumor-adjacent non-malignant prostate epithelium (TINT epithelium) was associated with prostate cancer survival." (PMID 26501565, 2015). "This appeared to be the case and high levels of LOX in the tumor-adjacent non-malignant prostate epithelium (TINT epithelium) were associated with shorter cancer specific survival in prostate cancer patients." (PMID 26501565, 2015). "Based on the role of hypoxia-associated molecules in cancer cell biological behaviour and clinical outcome, we assumed there might be an association, at the genetic and protein level, between HIF1A, LOX, CA9 and KDR genetic variants, the protein expression and prostate carcinoma." (PMID 28143503, 2017). "The functional role of LOX in prostate cancer could thus be context dependent." (PMID 26501565, 2015). "Some studies, however, suggest that LOX could also be inhibitory and a gradual loss of LOX is seen in prostate cancer metastases but not in the current one." (PMID 26501565, 2015). "High LOX activity has been correlated with ECM stiffness and poor prognosis in breast, head and neck, colorectal, and prostate cancer." (PMID 34200480, 2021). "Another three-signature panel containing urinary ACPP, urinary LOX, and serum PSA also demonstrated its ability in recognizing aggressive prostate cancer (AUC=0.82, 95% confidence interval 0.75 to 0.9)." (PMID 33204318, 2020). "Prostate carcinoma triggers an increase in hypoxia, which regulates HIF1A that in turn impacts downstream the expression of LOX, CAIX and VEGFR2 in tumor cells." (PMID 28143503, 2017). "The genotypic distributions for the putative functional target SNPs in HIF1A, LOX, CA9 and KDR were similar between nodular prostate hyperplasia and prostate carcinomas." (PMID 28143503, 2017).
prostate carcinoma (continued). "KLK4 activated protease‐activated receptor‐1 in WPMY1 cells increasing expression of several factors (FGF1, TAGLN, LOX, IL8, VEGFA) involved in prostate cancer progression." (PMID 28510269, 2017). "In vivo and in vitro experiments have demonstrated that the AA metabolites, particularly those generated through the LOX, such as 12-HETE, are critical to prostate cancer progression." (PMID 28697730, 2017). "As far as the authors of the present work are aware, there has been no extensive research on prostate cancer and LOX-inhibitory activity of S. scardica preparations of wild or in vitro-cultivated material." (PMID 41225814, 2025). "Activated LOX regulates cell migration, promotes cancer malignancy, and is correlated with ECM stiffness and poor prognosis in breast, colorectal, head and neck, and prostate cancer." (PMID 35138531, 2023). "The role of LOX as a prostate cancer biomarker is complex, since one study found that high LOX expression in the non-malignant prostate epithelium predicts a poor outcome in prostate cancer patients that are managed by watchful waiting." (PMID 38255186, 2023). "In particular, the LOX pro-peptide has been shown to decrease ERK and Akt signaling by inhibiting FGF-2 signaling upstream of these pathways in pancreatic, breast and prostate cancer cells." (PMID 33513979, 2021). "The role of LOX in prostate cancer is not established and both inhibitory and stimulatory effects are reported." (PMID 26501565, 2015). "Lysyl oxidase (LOX) has been shown to both promote and suppress tumor progression, but its role in prostate cancer is largely unknown." (PMID 26501565, 2015). "Indeed, by knocking down PHF19L, we observed significant induction of multiple genes known to promote changes in cytoskeleton and adhesion, extracellular matrix remodeling, invasion, and metastasis in prostate cancer (including SOX9, SOX4, MMP1, PLAU, EPCAM, CXCR4, LOX, and MET)." (PMID 32155117, 2020). "Hypoxia could thus be one explanation for the high LOX expression seen in the non-malignant prostate epithelium of some prostate cancer patients as hypoxia is common in the epithelial compartments in non-malignant and malignant human prostate tissue." (PMID 26501565, 2015). "Furthermore, although we have not observed an overrepresentation of cases with positive LOX expression in carcinomas compared to nodular prostate hyperplasia, the LOX immunoreactivity score was significantly higher in organ confined prostate carcinomas compared to nodular prostate hyperplasia." (PMID 28143503, 2017). "Our study suggests that LOX expression in the epithelium of the non-malignant part of the tumor-bearing organ could if validated in additional studies serve as an independent prognostic marker for prostate cancer." (PMID 26501565, 2015). "Therefore, despite functional SNPs in genes of pathways downstream of HIF-1α, such as KDR, LOX and CAIX, have not been studied so far in prostate carcinoma patients, they merit further research as they represent key molecules in hypoxia-generated stimulus in cancer." (PMID 28143503, 2017).